SLC1A5 (solute carrier family 1 member 5)
Diseases named in the same sentence as SLC1A5 in open-access papers (continued):
Sharing a sentence is not in itself a finding about the gene and the disease.
gastric cancer (28 papers, 2017 to 2025). A primary or metastatic malignant neoplasm involving the stomach. "Glutamine transporter SLC1A5 is also positively associated with immune infiltrates in gastric cancer, and inhibition of SLC1A5 improves antitumor immunity in TME." (PMID 37860928, 2023). "Knockdown SLC1A5 in gastric cancer cells suppressed cell proliferation, caused G0/G1 arrest and inhibited cell invasion as well as migration partly by inactivated mTOR/p-70S6K1 signaling pathway in vitro." (PMID 29100325, 2017). "In gastric cancer, quercetin induces ferroptosis in gastric cancer cells by targeting SLC1A5 and regulating the p-Camk2/p-DRP1 and NRF2/GPX4 axis." (PMID 40994946, 2025). "For example, patients with high expression of RGS4 and TXNIP exhibited a poorer prognosis in gastric cancer, while those with high expression of SLC1A5 have a better prognosis within five years." (PMID 36418919, 2022). "A recent study showed that knockdown of SLC1A5 inhibits cell proliferation and arrests cell cycle in G0/G1 phase in gastric cancer." (PMID 34282517, 2021). "Using the Kaplan-Meier plotter database, we further assessed the prognostic value of SLC1A5 expression in breast, ovarian, lung, and gastric cancer." (PMID 34367941, 2021). "Nevertheless, a higher expression of SLC1A5 in gastric cancer tissues has been correlated with clinicopathological features such as local invasion and lymph node metastasis." (PMID 33429909, 2021). "Our study showed that SLC1A5 was highly expressed in the specimen of gastric cancer patients and high expression of SLC1A5 in GC indicated poor clinicopathologic features." (PMID 29100325, 2017). "In conclusion, this is the first study to illuminate the role of SLC1A5 in gastric cancer in vitro and in vivo." (PMID 29100325, 2017). "SLC1A5 was up-regulated in gastric cancer tissues and was correlated with malignant features such as deeper local invasion, higher lymph node metastasis, advanced TNM stages and higher Ki-67 expression." (PMID 29100325, 2017). "By using subcutaneous xenograft mouse, the importance of SLC1A5 expression was assessed for both successful engraftment and growth of gastric cancer cells in vivo." (PMID 29100325, 2017). "SLC1A5 is highly expressed in gastric cancer tissues, and its high expression is correlated with poor prognosis." (PMID 29100325, 2017). "The expression level of SLC1A5 was detected in 70 gastric cancer paraffin-embedded tissues by immunohistochemistry and also was detected in gastric cancer cell lines by qRT-PCR and western blotting analysis." (PMID 29100325, 2017). "In this study, we firstly reported the oncogenic effects of SLC1A5 on gastric cancer development in vitro and in vivo." (PMID 29100325, 2017). "Targeting SLC1A5 restores ferroptosis sensitivity in gastric cancer." (PMID 40919170, 2025). "Among these, SLC1A5 (also known as ASCT2) serves as the primary transporter for glutamine, with its overexpression strongly linked to the growth, metastasis, and drug resistance of several cancers, including breast, lung, liver, and gastric cancers." (PMID 41041303, 2025). "SLC1A5-mediated ferroptosis inhibition drives gastric cancer progression." (PMID 40919170, 2025). "The current research on SLC1A5 in gastric cancer treatment is also focused on glutamine metabolism." (PMID 35305616, 2022). "Our data in vivo further supported the results of in vitro experiments that SLC1A5 could be a potential targeting therapy candidate for gastric cancer." (PMID 29100325, 2017). "In this study, we aimed to investigate the role of SLC1A5 in gastric cancer in vitro and in vivo." (PMID 29100325, 2017). "Our study also showed anti-proliferation effects of down-regulation of SLC1A5 in gastric cancer cells (HGC-27 and MGC-803), and this cytostatic consequences could be explained partly by suppressing the mTOR/p-70S6K1 signaling pathway." (PMID 29100325, 2017).
gastric cancer (continued). "Our results suggested that SLC1A5 might be considered as a new biomarker and also as a potential therapeutic target in gastric cancer." (PMID 29100325, 2017). "Our study also validated that SLC1A5 was an important glutamine transporter which promotes gastric cancer growth, and targeting SLC1A5 might have antitumor effects which partly by the inhibition of mTOR/p-70S6K1 signaling pathway." (PMID 29100325, 2017). "Thus, SLC1A5 may be considered as a potential biomarker and as a novel therapeutic target in gastric cancer." (PMID 29100325, 2017). "Our data suggested that SLC1A5 might be a potential therapeutic target in gastric cancer." (PMID 29100325, 2017). "Senescent endothelial cells secrete exosomal SLC1A5, which is taken up by tumor cells and suppresses ferroptosis in tumor cells via the EGFR/SRC/YAP1/GPX4 pathway, thereby promoting gastric cancer progression." (PMID 40919170, 2025).
pancreatic cancer (24 papers, 2017 to 2025). "Under conditions of nutrient deprivation, NEDD4L knockdown causes the accumulation of SLC1A5 in pancreatic cancer cells and stabilizes its protein level, and NEDD4L depresses autophagy and increases the oxygen consumption rate under cellular metabolic stress." (PMID 37190313, 2023). "It was reasonable to believe that SLC1A5 expression was closely associated with pancreatic cancer growth." (PMID 35419359, 2022). "Conversely, suppression of the SLC1A5 variant, a mitochondrial glutamine transporter, is sufficient to inhibit tumor growth by impairing glutamine metabolism in pancreatic cancer cells." (PMID 32943735, 2020). "Additionally, a recent report has revealed that a variant of SLC1A5, located in the inner mitochondrial membrane, plays a crucial role in metabolic reprogramming and mitochondrial glutamine metabolism in pancreatic cancer." (PMID 39431017, 2024). "Pancreatic cancer cell‐derived EVs upregulated SLC1A5 expression in PSCs, with a more pronounced effect in GEM‐resistant cells that was not altered by the addition of Asn alone." (PMID 40041969, 2025). "Upon bolus injection of alanine (6 mmole/kg), CEST MRI enhancement in vivo was higher in SLC1A5-overexpressing Pa20c pancreatic tumors than naïve tumors (p < 0.0001)." (PMID 41282145, 2025). "SLC1A5 mediates the cellular uptake of Asn; therefore, we determined the effect of pancreatic cancer cell‐derived EVs on SLC1A5 expression." (PMID 40041969, 2025). "Mechanistically, pancreatic cancer cell‐derived EVs mediate linc‐ZNF25‐1 to promote Asn uptake via the IGF2BP3/c‐Myc/SLC1A5 pathway in PSCs." (PMID 40041969, 2025). "This study demonstrates that pancreatic cancer cell‐derived EVs promote the uptake of Asn released from pancreatic cancer cells through the upregulation of SLC1A5 in PSCs, facilitating PSCs activation and pancreatic cancer resistance to GEM." (PMID 40041969, 2025). "Knockdown experiments targeting SLC1A5 expression have resulted in a drastic reduction in tumor cell proliferation, further underscoring its significance in pancreatic cancer pathogenesis." (PMID 38534987, 2024). "Elevated expression of SLC1A5 has been observed in surgically extracted tumor samples compared to adjacent tissues or benign pancreatic lesions, indicating its potential role in pancreatic tumor progression." (PMID 38534987, 2024). "SLC1A5 expression was more significantly upregulated in the pancreatic cancer (PC) cells (PANC-1, SW1990, BxPC-3, and ASPC-1) than in the normal pancreatic duct epithelia cell (HPDE6-C7)." (PMID 35419359, 2022). "The induction of SLC1A5 expression by hypoxia promotes the transport of mitochondrial glutamine to facilitate metabolism reprogramming in pancreatic cancer." (PMID 33783998, 2021). "A recent study also showed that oncogenic growth was dramatically suppressed by the knockdown of SLC1A5 and that overexpression of this gene restored cell growth, which indicated a critical role for SLC1A5 in pancreatic tumor growth." (PMID 33783998, 2021). "Recently, hypoxia-induced expression of the SLC1A5 variant was shown to be mediated by HIF-2α and to lead to metabolic reprogramming toward glutamine metabolism in pancreatic cancer cells." (PMID 32943735, 2020). "Furthermore, we will explore the regulatory impact of long noncoding RNAs (lncRNAs) in this context, specifically how pancreatic cancer cells modulate the IGF2BP3/c‐Myc/SLC1A5 signaling pathway through EV‐mediated linc‐ZNF25‐1 to enhance Asn uptake by PSCs." (PMID 40041969, 2025). "To further explore whether EV‐mediated linc‐ZNF25‐1 affects SLC1A5 expression in PSCs, we extracted EVs from pancreatic cancer cells with knocked down or overexpressed linc‐ZNF25‐1 and applied them to PSCs." (PMID 40041969, 2025). "Therefore, NEDD4L acts as a tumor-suppressor protein to inhibit the proliferation and survival of pancreatic cancer cells by ubiquitinating SLC1A5 expression." (PMID 37190313, 2023).
pancreatic cancer (continued). "A mice xenograft model also revealed that silencing SLC1A5 could notably suppress pancreatic tumor growth." (PMID 35419359, 2022). "More importantly, we found that SLC1A5 could enhance proliferative, migrative, and invasive abilities of pancreatic cancer (PC) cells, while it may increase the sensitivity to ferroptosis." (PMID 35419359, 2022). "Finally, the overexpression of SLC1A5 markedly promoted proliferation, migration, and invasion of pancreatic cancer cells." (PMID 35419359, 2022). "Based on lncRNA sequencing data of EVs, we confirmed that EVs derived from pancreatic cancer cells mediate the movement of linc‐ZNF25‐1 into PSCs and promote the uptake of Asn through the IGF2BP3/c‐Myc/SLC1A5 pathway." (PMID 40041969, 2025). "Consistent with this, the expression of Gln metabolism-related proteins, such as alanine-serine (Ser)-cysteine (Cys) transporter 2 (ASCT2/SLC1A5) and glutaminase 1 (GLS1), is significantly higher in pancreatic cancer cells than in normal cells." (PMID 41007358, 2025). "There are many related studies on pancreatic cancer worldwide, such as the recently identified super-enhancers such as JQ1, IBET, and SLC1A5 which can promote the EMT progression in pancreatic cancer." (PMID 35785176, 2022). "To further illustrate that SLC1A5 correlates with the uptake of Asn by PSCs to promote activation, we treated pancreatic cancer mice with PBS or V9302, respectively, and immunohistochemical staining of their tumors showed that both SLC1A5 and α‐SMA were attenuated in the V9302‐treated group." (PMID 40041969, 2025).
non-small cell lung carcinoma (23 papers, 2016 to 2026). A group of at least three distinct histological types of lung cancer, including non-small cell squamous cell carcinoma, adenocarcinoma, and large cell carcinoma. "SLC1A5 be a downstream target of miR-145-5p to influence the progression of non-small cell lung cancer." (PMID 41317550, 2025). "Solute carrier family A1 member 5 (SLC1A5) is primarily involved in glutamine transport, regulating cell growth and oxidative stress in non-small cell lung cancer (NSCLC)." (PMID 38534987, 2024). "For example, inhibition of SLC1A5 restricted the progression of non-small cell lung cancer by decreasing glutamine consumption, cell growth, and inducing cell autophagy and apoptosis." (PMID 35041678, 2022). "SLC1A5 is also related to non-small cell lung cancer prognosis." (PMID 31409775, 2019). "In contrast, it showed that SLC1A4 expression is downregulated in non-small cell lung cancer cells (NSCLC), while SLC38A1, SLC1A5, SLC7A5, and SLC7A11 were upregulated." (PMID 38705513, 2024). "The targeting of SLC1A5 can be performed by RNA interference and a small molecule inhibitor gamma-L-glutamyl-p-nitrosamides (GPNA) in non-small cell lung cancer (NSCLC) and human bronchial cell lines." (PMID 35223460, 2021).
glioblastoma (20 papers, 2014 to 2025). The most malignant astrocytic tumor (WHO grade IV). "Overexpression of SLC1A5 was also demonstrated in glioblastoma." (PMID 38705513, 2024). "Moreover, suppression of SLC1A5 by V9302 promotes the efficacy of anti-PD-1, making SLC1A5 a valuable prognostic biomarker and therapeutic target for glioblastoma." (PMID 38705513, 2024). "In conclusion, we propose that SLC1A5 may play a role in shaping the immunosuppressive tumor microenvironment and regulating the malignant progression of glioblastoma." (PMID 37566748, 2023). "Therefore, we conducted a comprehensive investigation to further explore the relationship between SLC1A5 and immune regulation in glioblastoma." (PMID 37566748, 2023). "Consistently, the IHC staining indicated that SLC1A5 was highly expressed in glioblastoma." (PMID 36566214, 2022). "However, there is limited research on the immunomodulatory role of SLC1A5 in glioblastoma." (PMID 37566748, 2023). "Therefore, we propose that SLC1A5 may induce immune suppression in glioblastoma through mechanisms involving T-cell exhaustion, upregulation of PD-L1, and the accumulation of Tregs and MDSCs." (PMID 37566748, 2023). "Therefore, inhibiting SLC1A5 may represent a potential novel strategy to prevent macrophage polarization toward the M2 phenotype and inhibit the progression of glioblastoma." (PMID 37566748, 2023).
liver cancer (19 papers, 2017 to 2025). An epithelial or non-epithelial malignant neoplasm that arises from the liver. "Upregulation of SLC1A5 levels is associated with increased glutamine uptake and dismal prognosis in hepatic cancer." (PMID 35560794, 2022). "Liver cancer cell lines with SLC1A5 expression knockdown or overexpression were constructed, and cell proliferation, colony formation, apoptosis, migration and drug sensitivity as well as in vivo xenograft tumor were measured." (PMID 38844930, 2024). "In line with the elevated expression of SLC1A5 and SLC7A5 in liver cancer, Trp levels were elevated in livers of mice upon MYC upregulation, as measured by tandem mass spectrometry (LC-MS/MS)." (PMID 38769298, 2024). "Using RNA-seq from the TCGA data set for liver cancer, we found that about 40% of patients with HCC had elevated SLC7A5, 50% had elevated SLC1A5 and 64% had either or both elevated." (PMID 38769298, 2024). "More importantly, in the present study, the single-cell sequencing analysis results implied that SLC7A11, SLC1A5, CARS1, RPL8 and TFRC were not only upregulated in liver cancer cells but also expressed in immune cells." (PMID 35847985, 2022).
triple-negative breast carcinoma (19 papers, 2015 to 2025). An invasive breast carcinoma which is negative for expression of estrogen receptor (ER), progesterone receptor (PR), and human epidermal growth factor receptor 2 (HER2). "The expression of SLC1A5 confers advantages in glutamine uptake in triple-negative breast cancer cells, accompanied by the attenuation of CD8+ and CD4+ T cell function." (PMID 39223142, 2024). "In triple-negative breast cancer, lower expression of SLC1A5 was correlated with better survival in both patients." (PMID 35864117, 2022). "Among these, SLC1A5 has received increased attention because its expression is upregulated in many cancer types, including triple-negative breast cancer." (PMID 31088535, 2019). "Furthermore, knockdown of SLC1A5 induced rapid cell death in basal-like triple-negative breast cancer cells in vitro and reduced xenograft implantation and subsequent growth in mice but had little effect on luminal cells." (PMID 39973065, 2025). "A recent study has shown that SLC1A5 is highly expressed in triple negative breast cancer." (PMID 34282517, 2021). "In addition, amino acid transporter proteins such as SLC1A5 and SLC7A5 are overexpressed in the triple-negative breast cancer samples, enabling tumor cells to meet the high demand for amino acids." (PMID 37731509, 2023).
ovarian carcinoma (18 papers, 2012 to 2025). A malignant neoplasm originating from the surface ovarian epithelium. "In conclusion, circ_0025033 interference repressed ovarian cancer cell malignant behaviors and glutamine metabolism via the hsa_miR-370-3p/SLC1A5 axis, indicating an underlying therapeutic target for the tumor." (PMID 36273140, 2022). "Meanwhile, high SLC1A5 expression was significantly associated with a better prognosis in ovarian cancer (OS HR = 0.85; 95% CI 0.74, 0.96; p = 0.011)." (PMID 34367941, 2021). "The value HR = 0.284 (P = 0.024) for SLC1A5 indicates that patients from that subgroup had a 71% reduced risk to die due to their ovarian cancer." (PMID 28609484, 2017). "High SLC1A5 levels were associated with poor prognosis for patients with ovarian cancer." (PMID 36273140, 2022). "Furthermore, the claudin-4/SLC1A5/LAT1 axis was linked to the transport of amino acids across the plasma membrane as one of the potential cellular processes that significantly decreased survival in ovarian cancer patients." (PMID 38867360, 2024). "In this process, SLC1A5 abolished the anti-ovarian cancer part of miR-370-3p and reduced glutamine metabolism." (PMID 39452837, 2024). "They suggested that circ_0025033 promotes ovarian cancer cell malignant behaviors and glutamine metabolism via the hsa_miR-370-3p/SLC1A5 axis." (PMID 37161350, 2023). "Increased expression of glutaminase and the glutamine transporter SLC1A5/ASCT2 has been observed in cisplatin-resistant ovarian cancer cells, and the inhibition of ASCT2 and glutaminase has been shown to sensitize these cells to cisplatin." (PMID 37233659, 2023). "Through molecular processes unrelated to cytotoxic drug sensitivity, SLC1A5 reduces ovarian cancer recurrence in the pathogenesis of the disease." (PMID 36523985, 2022). "In this research, SLC1A5 silencing inhibited ovarian cancer cell malignant behaviors, indicating a cancer-promoting role of SLC1A5 in ovarian cancer cells." (PMID 36273140, 2022). "The expression of ASCT2 (SLC1A5) is significantly increased in various tumors, including ovarian cancer." (PMID 36523985, 2022). "One study noted that circRNA_0072995 facilitates ovarian cancer progression by binding competitively to miR-122-5p, promoting the expression of SLC1A5." (PMID 36010849, 2022). "In the present study the relevance of HRNPM and SLC1A5 as prognostic factors for recurrent disease, survival and their impact on clinical and pathological features in a series of 123 patients with epithelial ovarian cancer in FIGO-stages I-II was evaluated." (PMID 28609484, 2017). "A retrospective cohort study was designed to investigate the prognostic effect of HNRPM and SLC1A5, and the association with clinical-pathologic characteristics in 131 patients with FIGO-stages I-II epithelial ovarian cancer." (PMID 28609484, 2017). "This is, to our knowledge, the first study indicating that SLC1A5 seems to be a prognostic factor for epithelial ovarian cancer." (PMID 28609484, 2017). "Additionally, it has been suggested that circ_0025033 facilitates the advancement of ovarian cancer by modulating the has-miR-370-3p/SLC1A5 pathway." (PMID 40422217, 2025). "In this study, circ_0025033 knockdown repressed ovarian cancer cell proliferation, metastasis, angiogenesis, and glutamine metabolism and accelerated apoptosis through the hsa_miR-370-3p/SLC1A5 axis, which is expected to offer a promising treatment strategy for patients with ovarian cancer." (PMID 36273140, 2022). "Additionally, SLC1A5 content was significantly reduced in ovarian cancer tissue, and its mRNA content was negatively correlated with the hsa_miR-370-3p level." (PMID 36273140, 2022). "Importantly, Huang and her colleagues stated that upregulation of miR-122-5p inhibited ovarian cancer process via targeting SLC1A5." (PMID 36273140, 2022). "Moreover, a recent study indicated that SLC1A5 (also called ASCT2) plays a promoter role in ovarian cancer." (PMID 36273140, 2022).